AIM2 (absent in melanoma 2)
Diseases named in the same sentence as AIM2 in open-access papers (continued):
Sharing a sentence is not in itself a finding about the gene and the disease.
glioblastoma (12 papers, 2012 to 2025). The most malignant astrocytic tumor (WHO grade IV). "Glioblastoma-associated antigens such as AIM2, BMI1, COX-2, TRP2, GP100, EGFRv III, EZH2, LICAM, Livin/Livin β, MRP3, NESTIN, OLIG2, and SOX2 are present on these human GSCs." (PMID 22474481, 2012). "The authors also highlighted that there was a significant inverse correlation between methylated CpG loci and AIM2 expression in glioblastoma patients." (PMID 40002808, 2025). "What’s more, AIM2 inflammasome inhibits the proliferation of cancer cells in glioblastoma multiform." (PMID 36248785, 2022). "AIM2 regulates tumor cell proliferation in glioblastoma multiforme." (PMID 34680930, 2021). "An independent randomized double-blind phase II trial involving a larger cohort of glioblastoma patients led to comparable conclusions using autologous DCs pulsed with six synthetic peptide epitopes derived from glioblastoma-associated antigens MAGE-1, IL13Rα2, AIM-2, TRP-2, gp100, and HER-2." (PMID 41514632, 2025). "In this context, it was observed that the treatment with TTFields led to both AIM2 assembly and activation and the induction of the cGAS-STING pathway, both responsible for the membrane-damaged cell death of glioblastoma cancer stem-like cells derived by patients." (PMID 40002808, 2025). "One research hypothesizes that Tumor Treating Fields (TTFields), approved in combination with adjuvant temozolomide chemotherapy for newly diagnosed glioblastoma (GBM) patients, induced a significant improvement in overall survival after AIM2 and cGAS activation." (PMID 39857785, 2025). "The most advanced DC vaccine, ICT-107, uses autologous DC pulsed with six peptides, two HLA-A1-restricted and four HLA-A2-restricted, which derive from protein expressed and predicted to be abundant in GBM and glioblastoma cancer cells: gp100, MAGE-1, AIM2, HER2, IL13Ra2 and TRP2." (PMID 35454848, 2022).
diabetes (11 papers, 2018 to 2025). "Metformin, a prominent drug in diabetes management, has been shown to block dsDNA/AIM2-mediated pyroptosis in macrophages associated with diabetes." (PMID 39201755, 2024). "This acceleration in STZ-induced diabetes development in AIM2-deficient mice occurred through enhanced gut permeability and increased bacterial translocation to the pancreatic lymph nodes." (PMID 34177937, 2021). "In contrast to NLRP3-deficient C57BL/6 mice, AIM2-deficient C57BL/6 mice had accelerated STZ-induced diabetes development, compared to wild-type control mice, implying that ASC regulates inflammasome activation." (PMID 34177937, 2021). "Conclusively, inhibition of PTP1B via Viscosol could attenuate meta-inflammation by suppressing the aberrant NLRP3 and AIM2 inflammasome signaling in diabetes-linked pathophysiology." (PMID 40173145, 2025). "Overall, our results demonstrated that Viscosol exhibits anti-inflammatory activity by reversing the NLRP3 and AIM2-mediated inflammation in diabetic neuro and nephropathy, thus making it a potent therapeutic drug for the treatment of diabetes-linked pathophysiology." (PMID 40173145, 2025). "However, more studies are needed to confirm the association of AIM2 with IR and other types of diabetes." (PMID 36993972, 2023). "According to data from the GEO datasets, AIM2 showed relatively high expression levels in the adipose tissue of older adults with diabetes, while exhibiting lower FHOD3 expression levels than those of the older healthy group." (PMID 41462520, 2025). "Recent studies on diabetes and AIM2 have shown that AIM2 expression in monocytes and mitochondrial DNA (mtDNA) levels in the serum are elevated in T2D patients." (PMID 41462520, 2025). "The high glucose environment generated by diabetes can also induce dysfgunction of macrophages through cytoplasmic dsDNA/AIM2-related apoptosis, accelerating the aging process and inducing a systemic pro-inflammatory state." (PMID 36993972, 2023). "In our logistic regression with covariants, the reduction in total methylation or some CpGs methylation in the NLRP3, AIM2 and ASC promoters increased the risk of diabetes or diabetic vascular complications to a varying degree." (PMID 30555415, 2018). "AIM2 and FHOD3 could serve as novel diagnostic and therapeutic targets for older adults with diabetes." (PMID 41462520, 2025). "Furthermore, research findings have indicated that metformin may regulate the AIM2 pathway and alleviate diabetes-related inflammatory responses." (PMID 41462520, 2025). "On the contrary, Aim2 was found to be down-regulated in NOD compared to B6 ES cells, and was previously shown to be protective for B6 mice from developing diabetes in the presence of Steptozotocin, supporting the gene expression profiles predisposing to diabetes in NOD mice." (PMID 32796510, 2020). "At present, there are few studies on AIM2 and T1DM or other types of diabetes, and AIM2 has been found to play a protective role in the STZ-induced T1DM model in an animal experiment." (PMID 36993972, 2023). "Together, our findings show a regulatory role of AIM2, mediated by IL-18, in shaping gut microbiota and reducing bacterial translocation and proinflammatory response against insulin-producing β cells, which ultimately results in protection against T1D onset in an STZ-induced diabetes model." (PMID 32295112, 2020).
Salmonella Infections (11 papers, 2017 to 2024). Infections with bacteria of the genus SALMONELLA. "The role of AIM2 in barrier function has been reported in the context of Salmonella infection in the colon, albeit with its expression having an opposing effect (i.e. promoting barrier integrity)." (PMID 36967659, 2023). "Activation of NLRC4 inflammasome by Salmonella infection and AIM2 inflammasome by exposure to poly(dA:dT) resulted in comparable caspase-1 cleavage between WT and Abcb1b–/– cells (data not shown)." (PMID 36038196, 2022). "Additional research has demonstrated that AIM2 can inhibit the Akt signaling pathway in an inflammasome-independent manner, thereby enhancing intestinal epithelial integrity and augmenting the host’s resistance to Salmonella infection." (PMID 38918243, 2024). "Furthermore, we found that inhibition of S1PR3 enhanced dsDNA-induced AIM2 inflammasome and salmonella infection-induced NLRC4 inflammasome activation, as indicated by enhanced caspase-1 cleavage." (PMID 36798132, 2023). "The results revealed that SMI-4a had the inhibitory effect on AIM2 inflammasome and NLRC4 inflammasome, trigged by poly (dA:dT) transfection or Salmonella infection, resulting in a decrease in IL-1β production." (PMID 37422640, 2023). "We also found that Ori could not suppress NLRC4 or AIM2 inflammasome activation induced by Salmonella typhimurium (Salmonella) infection or poly A:T transfection, respectively." (PMID 29959312, 2018). "Additionally, AIM2 has been reported to have a role in preserving epithelial integrity of the intestinal barrier during Salmonella infection, but it is not clear whether this defence mechanism involves inflammasome or non‐inflammasome‐dependent functions of AIM2." (PMID 32185892, 2020). "The results showed that GlcN not only inhibited NLRP3 inflammasome but also reduced IL-1β secretion in AIM2-, non-canonical- and NLRC4-inflammasome activated J774A.1 macrophages, which are stimulated by poly(dA:dT) and LPS transfection or by Salmonella infection, respectively." (PMID 30944389, 2019).
nasopharyngeal carcinoma (10 papers, 2012 to 2025). A carcinoma arising from the nasopharyngeal epithelium. "The high expression of AIM2 was associated with a higher survival rate in EBV-induced nasopharyngeal carcinoma (NPC)." (PMID 35070978, 2021). "Furthermore, it has been shown that the autophagy-dependent secretion of IL-1β by the AIM2 inflammasome requires the microtubule associated protein EB1 in nasopharyngeal carcinoma and monocyte cell lines." (PMID 29750813, 2018). "Compared with normal tissues, components of NLRP3 and AIM2 inflammasomes were highly expressed in nasopharyngeal carcinoma tissues, which correlated with an increased chance of survival in nasopharyngeal carcinoma." (PMID 35847844, 2022). "In nasopharyngeal carcinoma (NPC), AIM2-induced IL-1β in tumor cells plays a crucial role in tumor control by recruiting neutrophils." (PMID 36386141, 2022). "Here we show that the NLRP3, AIM2 and RIG-I inflammasomes are overexpressed in Epstein-Barr virus (EBV)-associated nasopharyngeal carcinoma (NPC), and expression levels correlate with patient survival." (PMID 23065753, 2012).
ovarian carcinoma (10 papers, 2016 to 2025). A malignant neoplasm originating from the surface ovarian epithelium. "A study analyzing pyroptosis genes from a TCGA cohort of ovarian cancer patients demonstrated that AIM2 was upregulated in ovarian tumors and contributed to a longer overall survival." (PMID 40492347, 2025). "In our comparative bioinformatic analysis between endometriosis and ovarian carcinoma, we found AIM2 diversely expressed in the two groups of data, suggesting a role of AIM2 in promoting the progression of ovarian carcinoma." (PMID 29423077, 2018). "The network based approach identified two 7-gene functional interaction modules (31: DCLRE1A, EXO1, KIAA0101, KIN, PCNA, POLD3, POLD2; 35: DKK3, FABP3, IRF1, AIM2, GBP1, GBP2, IRF2) that are associated with prognosis of ovarian cancer patients." (PMID 27806724, 2016). "In this context, AIM2 could represent a potential therapeutic target for ovarian carcinoma treatment." (PMID 40002808, 2025). "Collectively, these studies highlight that the AIM2 inflammasome might have a role in ovarian cancer establishment and progression and could be used as a valuable biomarker for patients’ prognosis." (PMID 40002808, 2025). "For instance, the early microenvironment of ovarian cancer may induce the production of DAMPs, which may subsequently activate AIM2 and NLRP3 inflammasomes." (PMID 37752941, 2023). "Antiangiogenic therapy effectiveness in ovarian cancer is predicted by AIM2." (PMID 37752941, 2023). "The results of the two experiments indicate that AIM2 could be an effective biomarker for guiding ovarian cancer treatment." (PMID 35406422, 2022). "In a previous study, the high expression level of AIM2 and NLRP3 was significantly correlated with poor PFS and disease progression of EOC which demonstrated a key role of the dysregulated inflammasome in modulating the malignant transformation of endometriosis-associated ovarian cancer." (PMID 35406422, 2022). "This study also showed that CXCL9 protein secretion occurred from ovarian cancer cell lines after the addition of IFNG and TNFA using cell culture, which is substantiated by our findings that CXCL9 as well as AIM2 are target genes for IFNG." (PMID 40492347, 2025). "provided a novel gene signature including 7 PRGs (AIM2, PLCG1, ELANE, PJVK, CASP3, CASP6, and GSDMA) for predicting the prognosis of ovarian cancer (OC) patients and laid a foundation for further studies of the relationships between PRGs and immunity in OC." (PMID 35912258, 2022). "To evaluate the clinical significance of the identified inflammasome-related genes in ovarian cancer transformation, we collected a cohort of clinical samples (ES, n = 13; CCC, n = 15; EC, n = 15) and immunostained them with anti-AIM2 antibody." (PMID 29423077, 2018). "Therefore, we performed methylation analysis of 51 PYAGs and showed that AIM2, CASP1, CASP8, GSDMC and NLRP6 exhibited hypomethylation in ovarian cancer, which may provide a new theory to explore the methylation of above five genes to improve potential antitumor efficacy of OC." (PMID 36707884, 2023).
Arthritis (9 papers, 2015 to 2024). Inflammation of a joint. "In a mouse model of chronic polyarthritis induced by DNase II deficiency, arthritis-susceptible mice that were deficient in AIM2 exhibited significantly reduced signs of joint inflammation and associated histopathological manifestations." (PMID 39450183, 2024). "In fact, induction of experimental arthritis in Il10-KO mice caused a significant increase in the expression of Nalp3, Aim2 and Caspase-144." (PMID 32385413, 2020). "As such, Dnase2-deficient mice being wild type for Aim2 displayed a significant mean arthritis score of 1.8 compared to Dnase2-competent mice." (PMID 26114879, 2015). "Altogether our data show that AIM2 plays an important role in the recognition of endogenous DNA species in the context of Dnase2-/- associated arthritis, thereby establishing AIM2 as a DAMP sensing PRR." (PMID 26114879, 2015). "Moreover, arthritis induced by DNase II deficiency, which is associated with accrual of self-DNA, is attenuated by AIM2 ablation." (PMID 31520179, 2019). "For example, NLRP3 and AIM-2 are both upregulated in the synovium of IL-10-deficient mice exposed to antigen-induced arthritis, and osteoclast differentiation from bone marrow cells isolated from these mutant mice is blunted by the inhibitors of NLRP3 and AIM-2 inflammasomes." (PMID 31520179, 2019). "In arthritis models, the AIM2 inflammasome is reported to contribute to joint inflammation in a model of chronic polyarthritis, where AIM2 detects self-DNA." (PMID 35455985, 2022). "Inappropriate recognition of cytoplasmic self-DNA by AIM2 contributes to the development of psoriasis, dermatitis, arthritis, and other autoimmune or inflammatory diseases." (PMID 33162829, 2020). "With increasing age, signs of chronic polyarthritis progressed to a score of up to 3.4 in the Aim2+/+x Dnase2-/- cohort at 15 months, whereas Aim2-/-x Dnase2-/- mice showed greatly reduced signs of arthritis (mean score of 0.5)." (PMID 26114879, 2015). "Importantly, Myr administration relieved arthritis symptoms and inhibited AIM2 expression in the synovium of CIA mice." (PMID 36120327, 2022). "In the additional absence of Aim2, Dnase2-deficient mice (Aim2-/-x Dnase2-/-) showed a significant reduction in their signs of arthritis with a clinical score that was comparable to Dnase2-competent mice." (PMID 26114879, 2015). "Arthritis-prone mice lacking AIM2 displayed strongly decreased signs of joint inflammation and associated histopathological findings." (PMID 26114879, 2015). "In line with the arthritis scores and the pro-inflammatory cytokine profile, histological signs of arthritis, macrophage infiltration and Mmp3 expression were largely decreased in the absence of Aim2." (PMID 26114879, 2015). "However, studies regarding AIM2 inflammasome on arthritis were still limited, especially investigations on clinical patients have not been reported, which leads to the AIM2 inflammasome in the pathogenesis of RA is not well demonstrated." (PMID 33162829, 2020).
chronic kidney disease (9 papers, 2019 to 2025). Impairment of the renal function secondary to chronic kidney damage persisting for three or more months. "The inflammasome activation, including AIM2 also contributes to the chronic kidney disease (CKD) and ischemia-reperfusion-induce kidney damage." (PMID 33643304, 2020). "In a similar manner, chronic kidney disease (CKD), which was characterized by inflammation and renal fibrosis, involved AIM2-mediated inflammasome activation and endoplasmic reticulum stress (ERS), both of which played crucial roles in renal fibrosis." (PMID 39600708, 2024). "Although AIM2 inflammasome has a protective effect in infectious diseases, they are harmful in some aseptic inflammatory diseases, including atherosclerosis, chronic kidney disease (CKD), skin disease, liver disease, neuroinflammation, and others." (PMID 36993972, 2023). "To date, studies have focused on the role of AIM2 inflammasome in the pathogenesis of chronic kidney disease (CKD); however, the explicit mechanism of the AIM2 inflammasome in AKI remains unknown." (PMID 35155498, 2022). "While efferocytosis is typically anti-inflammatory, macrophages can uptake leaked intracellular contents from necrotic cells, such as DNA, which can activate the absent-in-melanoma 2 (AIM2) inflammasome protein, leading to inflammation in chronic kidney disease." (PMID 38673935, 2024). "The AIM2/NLRP3 inflammasomes are also a key component in the development and progression of chronic kidney disease (CKD)." (PMID 40264103, 2025). "In addition, the AIM2 expression was found in kidneys from patients with diabetic or nondiabetic chronic kidney disease (CKD)." (PMID 30965677, 2019).